ABCC1 (ATP binding cassette subfamily C member 1 (ABCC1 blood group))
Diseases named in the same sentence as ABCC1 in open-access papers (continued):
Sharing a sentence is not in itself a finding about the gene and the disease.
cancer (continued). "Finally, CERS4 knockdown in doxorubicin-resistant MCF-7/ADR cells resulted in reduced activation of cancer-associated pathways (NF-κB, Akt/mTOR, β-catenin, and EMT) and diminished chemoresistance, accompanied by ABCB1 and ABCC1 downregulation." (PMID 37885013, 2023). "Our findings also indicate that ABCC1 regulation may be a viable approach to improve the effectiveness of chemotherapy in cancer treatment." (PMID 38102848, 2023). "Based on this result, we could conclude that CDKN1B, PIAS4, CTBP2, and ABCC1 could be the potential source for ZNF143 (because these genes link more biological functions) to alter the major cancer signaling pathways." (PMID 36675976, 2022). "Taken together, our ex vivo data indicate a possible favorable MDR-combating capacity of encorafenib, which might be beneficial for cancer patients genotyped for the high intratumoral levels of ABCC1." (PMID 36559089, 2022). "Indeed, in the present study, the sensitivity to eribulin was associated with the ABCB1, ABCC1, p-AKT, p-NFκB, and NFκB expression levels in the blood cancer cells." (PMID 36551566, 2022). "Based on the cytotoxicity assays performed on the ABCC1-overexpressing cancer cells, COTI-2 and COTI-NMeCy could be identified as ABCC1 substrates most probably based on the recognition and efflux of their GSH-copper(II)-TSC ternary species." (PMID 36139615, 2022). "At the same time, these results suggest that talazoparib might be a highly effective dual-activity MDR antagonist in cancer cells with ABCC1 and/or ABCG2 overexpression." (PMID 36430819, 2022). "Here, CDKN1B, PIAS4, CTBP2, and ABCC1 could be the potential source for ZNF143 to alter the major cancer signaling pathways." (PMID 36675976, 2022). "The significant contribution of thethree major ABC transporters, including ABCB1 (P-glycoprotein/P-gp/MDR1), ABCG2 (Breast Cancer Resistance Protein/BCRP/MXR), and ABCC1 (Multidrug Resistance Protein 1/MRP1) to MDR in cancer chemotherapy is well documented in vitro studies." (PMID 36104708, 2022). "An MTT-based cell viability assay showed that ABCC1 overexpression has the ability to desensitize both cancer cell line and gene-transfected cell line to betulin and that this betulin-induced resistance can be antagonized by a known ABCC1 inhibitor MK571 at 25 μM." (PMID 33718236, 2021). "In pan-cancer analysis of 32 cancer species, ABCC1, CHAC1, and GSS may act as hallmarks to activate tumor immune reactions and reshape the tumor environment in LGG, LIGC, BRAC, LUAD, LUSC, and UVM." (PMID 34386492, 2021). "ABCC1 multidrug resistance protein (1/MRP1) is a member of the C subfamily of ABC transporters that is capable of contributing to chemotherapeutic failure in various cancers by regulating the efflux of chemotherapeutic drugs." (PMID 34386492, 2021). "Based on the overlapping cancer spectrum, we postulated that the overexpression of ABCC1 may attenuate the anticancer efficacy of betulin." (PMID 33718236, 2021). "Thus cancer MDR is often associated with overexpression of ABC transporters such as ABCB1, ABCG2 and ABCC1, which have been proved to mediate the efflux of structurally distinct chemotherapeutic agents." (PMID 34631561, 2021). "Among them, ABCB1 (P-glycoprotein; P-gp, MDR1), ABCC1 (multidrug resistance-associated protein 1; MRP1), and ABCG2 (breast cancer resistance protein; BCRP, mitoxantrone resistance protein; MXR) are the major transporters involved in MDR, in cancer cells." (PMID 34830383, 2021). "The transporter ABCC1 has also been shown to regulate cancer-cell proliferation." (PMID 32587767, 2020). "The ability of ABCC1 to transport these bioactive lipids and steroids might therefore suggest additional roles for the transporter during cancer development and progression, beyond chemotherapeutic drug resistance." (PMID 32718079, 2020). "Overexpression of ABCB1, ABCC1, and/or ABCG2 is a major cause of MDR in cancer." (PMID 33066132, 2020).
cancer (continued). "Indeed, in vivo expression of ABCC1 correlates with drug resistance and/or poor prognosis in a range of cancers." (PMID 32718079, 2020). "Previous studies have shown that TAOK3 and ABCC1 are involved in various cancers." (PMID 29643985, 2018). "In all cancer cell lines, the ABCC1 promoter was found to be unmethylated." (PMID 27689338, 2016). "In addition to ABCB1/MDR1, ABCC1/MRP1 is overexpressed in several drug-resistant cancer cells and can confer resistance to several antitumor drugs, such as anthracyclines, vinca alkaloids, and camptothecins." (PMID 26305906, 2015). "As reported, ABCG2 and ABCC1 transporters also lead to cancer MDR." (PMID 26296969, 2015). "Three ATP-binding cassette (ABC) drug transporters have been associated with drug resistance in most cancers, and the ABCB1 (p-glycoprotein/MDR1), ABCC1 (MRP1) and ABCC2 (MRP2) subfamilies have been shown to be involved in the development of cisplatin resistance." (PMID 25638155, 2015). "High expressions of ABCG2, ABCB1, or ABCC1 were validated in CSCs in various cancers, and the ability of CSCs to extrude Hochest 33342 by ABCG2 was used to develop the “side population” method, which is frequently used to isolate stem-like cells from primary tumors or cancer cell lines." (PMID 26431273, 2015). "Comparing tumor and normal tissues, three of the five analyzed genes showed a significant lower expression in tumors than in healthy control tissues (ABCB1, p<0.0001; ABCC2, p<0.005; ABCG2, p<0.0001), whereas ABCC1 expression was significantly up-regulated in the carcinomas (p<0.0001)." (PMID 25275603, 2014). "Our results indicate that ABCC1 could be a gene biomarker of arsenic response, as well as a potential chemotherapeutic target when using arsenic trioxide in cancer treatment, for APL and possibly other tumor types." (PMID 20707922, 2010). "Because kaempferol sensitizes OVCAR-3 cancer cells' response to cisplatin treatment, the effect on gene expression by cisplatin and/or kaempferol was further evaluated by analyzing mRNA levels of ABCC1, ABCC5, ABCC6, NFκB1, cMyc and CDKN1A genes." (PMID 20459793, 2010). "ABCC1, as an ATP binding cassette protein, is believed to participate in chemotherapeutic agents transportation, including arsenic trioxide; and possibly contributes to the chemoresistance in cancer treatment." (PMID 20707922, 2010). "The results above indicated that vandetanib could enhance the sensitivity of MDR cancer cells to certain ABCC1 and ABCG2 substrate anticancer drugs." (PMID 19390592, 2009). "MDR cancer cells overexpressing ABCC1 or ABCG2 and their sensitive parental cell lines were used." (PMID 19390592, 2009). "Additionally genes DPYD, ABCC1, FTL and ICAM3 whose expression is shown to be associated with outcome of cancer treatment were also observed in the data set." (PMID 18782426, 2008). "Moreover, miR‐381‐mediated downregulation of LRRC‐4 decreases the expression of multidrug resistance‐associated proteins including ATP‐Binding Cassette Subfamily C Member 1 (ABCC1), ABCC2 and ABCG1, along with cluster of differentiation 133, a marker of cancer stem cells." (PMID 35014178, 2022). "Nowadays, the largest challenge for cancer drug treatment is MDR initiated by the elevation of the ATP-binding cassette (ABC) efflux transporters, including P-glycoprotein (P-gp/ABCB1), multidrug resistance-associated protein 1 (MRP1/ABCC1) and breast cancer resistance protein (BCRP/ABCG2)." (PMID 34026649, 2021). "Across different cancer types, MAPK/ERK and PI3K-AKT signaling have been shown to increase drug resistance via altered expression of Bcl-2 family proteins or increased activity of the ATP-binding cassette C 1 (ABCC1) transporter/multidrug resistance-associated protein 1 (MDR1)." (PMID 32528884, 2020). "ABCC5 is in the same family as the known drug efflux pump ABCC1/MRP1 and is thought to confer chemoresistance through reducing effective concentrations of chemotherapeutic drugs in cancer cells." (PMID 41009771, 2025).
cancer (continued). "Their research indicated that some epigenetic drivers, like regulatory regions of ABCC1 and VEGFA, appeared in pan-cancer, while some epigenetic regulators, like FGF19, ASAP2 and EN1, and the PBX3 motif, are cancer specific." (PMID 40041484, 2025). "This includes the upregulation of main types of ABC transporters (e.g., ABCB1, ABCC1, and ABCG2), which provides the efflux of chemotherapeutic agents from cancer cells." (PMID 41154409, 2025). "Well-characterized members of this transporter family include P-glycoprotein (P-gp, also known as MDR-1 or ABCB-1), MRP-1 or ABCC-1, and BCRP or ABCG2, all of which are commonly overexpressed in drug-resistant cancer cells." (PMID 40725123, 2025). "In all MDR cancer cell lines tested, incubation of KSQ‐4279 had few effects on ABCB1/ABCG2/ABCC1 expression both in mRNA level and protein level, even given the treated concentration of KSQ‐4279 higher to 50 μM or the incubated time longer to 72 h." (PMID 41328326, 2025). "Among those subfamilies, the three major types involved in cancer drug resistance are ABCB1, ABCC1, and ABCG2, which represent MDR1, MRP1, and BCRP proteins, respectively." (PMID 38326737, 2024). "ABCB1, ABCC1, and ABCG2, are key members of the ATP-binding cassette (ABC) transporter family, which are crucial for multidrug resistance in cancer cells." (PMID 39574476, 2024). "The expression of specific target genes, including Bcl-2, MDR1/ABCB1, and MRP1/ABCC1, which regulate apoptosis, autophagy, drug efflux, epithelial to mesenchymal transition (EMT), and cancer stem cells (CSCs), leads to the development of MDR." (PMID 38572428, 2024). "Some studies have suggested that upregulation of ABC family proteins such as ABCB1, ABCC1 and ABCG2, which transport chemotherapeutic drugs out of cancer cells, is the main reason for chemoresistance in cancer cells." (PMID 38228910, 2024). "Mechanistically, the combination of MRTX849 and dasatinib inhibited JUN-dependent expression of ABCC1 and CCND1 in multidrug-resistant cancer cells." (PMID 39661665, 2024). "The binding sites of ABCB1, ABCC1 and ABCG2 are highly flexible and known to bind and transport diverse compounds including anti-cancer drugs." (PMID 38766631, 2024). "ABCC1, also known as multidrug resistance protein 1 (MRP1), mediate chemotherapy resistance via efflux cancer drugs in the presence of glutathione." (PMID 38824544, 2024). "The expression of ABCC1 in TR28 was an exception, as non-cancer cells in this culture showed a high intrinsic expression of ABCC1." (PMID 38893104, 2024). "The overexpression of P‐gp (ABCB1), ABCC1 and ABCC4 in K562/FLM cells suggests the classic MDR phenotype observed in many resistant cancer cells." (PMID 39046364, 2024). "Some epigenetic drivers appeared in multiple cancers (for example, regulatory regions of ABCC1 and VEGFA; GATA6 and FOX-family motifs), whereas others were cancer specific (for example, regulatory regions of FGF19, ASAP2 and EN1, and the PBX3 motif)." (PMID 37914932, 2023). "ABCC1 and MAP1B are reported gene targets of miR-9-5p that have been found to predict chemoresistance in cancer." (PMID 37081981, 2023). "CSCs efficiently express ABC transporter proteins, such as MDR1/ABCB1, MRP1/ABCC1, and ABCG2, that belong to multidrug resistance proteins and ensure cancer cells’ resistance to anticancer therapy." (PMID 37626893, 2023). "The PI3K/Akt pathway enhances the biological basis of cancer by effectively expressing ABC transporters, including P-gp (ABCB1), MRP1 (ABCC1), and BCRP (ABCG2)." (PMID 36693064, 2023). "Increased ABC transporter expression, including ABCB1 (P-glycoprotein/MDR1), ABCC1 (MRP1), and ABCG2 (BCRP), is one of the most well-established strategies for cancer cells to acquire multidrug resistance (MDR)." (PMID 36902427, 2023).
cancer (continued). "The high specificity of the interaction between ABCC1 and BCL-2 inhibitors suggests that efflux transporters hold great potential for the development of rational cancer treatments that involve newly approved small molecule inhibitors." (PMID 37726279, 2023). "Among them, three subfamilies commonly involved in cancer MDR are P-glycoprotein (P-gp), multidrug resistance protein 1 (MRP 1 or ABCC1), and breast cancer resistance protein (BCRP or ABCG2)." (PMID 37760764, 2023). "Secondly, because cancer SP cells highly express three ATP-binding cassette (ABC) transporters, ABCB1 (also known as MDR1/P-glycoprotein), ABCC1, and ABCG2 (also known as BCRP), they are thought to be chemo-resistant tumor-initiating cells." (PMID 35659728, 2022). "The overexpression of ABC transporters (ABCB1, ABCG2, and ABCC1), along with CYP3A4, is frequently observed in various cancer types." (PMID 36559089, 2022). "The ABC family members ABCB1, ABCC1, and ABCG2, which are related to drug resistance in several types of cancer, were first evaluated in MDA-MB-231 cells." (PMID 36291159, 2022). "Similar to its functional homologues ABCB1 and ABCC1, ABCG2 also has a notorious function in extruding antitumor drugs from various cancer cells, which can result in multidrug resistance, a severe obstacle in cancer treatment." (PMID 36294746, 2022). "Amongst the nine primary transporters (ABCC1-6, ABCC10-12, or MRP 1-9) in the ABCC family, ABCC5 was found to transport nucleoside monophosphate analogues and produce cancer drug resistance." (PMID 35141332, 2022). "Most prominent and well-studied are ABCB1, ABCC1, and ABCG2, not only due to their contribution to the multidrug resistance (MDR) phenotype in cancer, but also due to their contribution to AD." (PMID 34977908, 2021). "The inhibition of this demethylase in the presence of I-CBP112 prevented the repression of ABCC1 and ABCC10 and, to a considerable extent, cancer cells’ sensitization to drugs." (PMID 34572840, 2021). "ABC transporters including ABCB1, ABCC1, ABCC2, and ABCG2 are involved in the reduction of chemosensitivity in cancer cells." (PMID 34066059, 2021). "Another critical mechanism involves the increased outflow of drugs from cancer cells by upregulated transport proteins that rely on specific energy sources such as ABCB1, ABCC1, and ABCG2." (PMID 34306145, 2021). "Acting as one of the main agents of MDR in cancers, the overexpression of ABC transporters such as ABCB1, ABCC1, and ABCG2 have been reported in CSCs that protect cells from cytotoxic agents." (PMID 34051847, 2021). "The development of cancer chemoresistance is upregulated by several ABC transporters including ABCB1, ABCC1, ABCC2, and ABCG2." (PMID 34066059, 2021). "In recent years, more ABC transporters have been identified to be related with MDR in cancer besides ABCB1, ABCG2, and ABCC1." (PMID 33593355, 2021). "ABC family members including ABCB1, ABCC1, ABCC2, ABCC3, and ABCG2 were critical for CDDP resistance of cancer cells." (PMID 33754002, 2021). "For ABCC1-mediated MDR cancer cells, we used KB-3-1 (parental) and KB-CV60 (cepharanthine + vincristine-selected ABCC1-mediated MDR cells)." (PMID 33364237, 2020). "Since upregulation of ABC-transporters is a common mechanism of cancer drug resistance, we used qRT-PCR to examine the mRNA levels of the most frequently observed transporters, ABCB1, ABCC1 and ABCG2, in our CDK7 inhibitor-resistant cell lines." (PMID 31530935, 2020). "Most studies investigating DNA methylation of ABC transporters in cancer are limited to ABCB1, ABCC1, and ABCG2, only few studies hint at aberrant DNA methylation of other members of the ABC transporter family." (PMID 33066132, 2020). "Expression of the major ABC transporters, including ABCA1, ABCB1, ABCC1, ABCC2, ABCC3 and ABCG2, was assessed in chemoresistant cancer cells transfected with si-ERRγ." (PMID 32206097, 2020).
cancer (continued). "In 2N patients, we saw aberrations, e.g., in Chr.16p13.11, that harbor at least four genes (ABCC1, FOPNL, MYH11, KIAA0430) involved in cancer development or that are present in rare CNVs in cancer patients." (PMID 32577795, 2020). "This phenomenon is witnessed in tumors overexpressing ABC family of transporters such as P-gp, MRP1/ABCC1 and BCRP/ABCG2 and is one of the promising procedures to treat drug resistant cancer cells." (PMID 32742605, 2020). "ABCB1, ABCC1, and ABCG2 are ATP-binding cassette (ABC) transporters functioning as efflux pumps, lowering intracellular accumulation of various anti-cancer drugs." (PMID 33066132, 2020). "The ATP-binding cassette (ABC) transporters ABCB1 (also known as P-glycoprotein or MDR1) and ABCC1 (also known as MRP1), major mediators of drug resistance in cancer, were discovered in drug-adapted cell lines." (PMID 31581737, 2019). "To this end, we explored the potential mechanism and chemosensitizing effect of TMP195 in multidrug-resistant cancer cells overexpressing ABCB1, ABCC1 or ABCG2." (PMID 31905792, 2019). "Overall, these results suggested that SP1 activated ABCC1 and stimulated the expression of the CCNE1, ERF, and MYB genes, which have been shown to be related to chemoresistance and cancer relapse." (PMID 31118037, 2019). "Among them, ABCB1, ABCC1 and ABCG2 are highly involved in the acquisition of multidrug resistance (MDR) to cancer chemotherapeutics." (PMID 34322663, 2019). "Efflux transporters (e.g., P-gp/ABCB1, ABCC1, and ABCG2) and influx transporters (e.g., SLC22A16) are involved in Dox resistance in cancer cells." (PMID 31293428, 2019). "Similar to ABCB6, ABCC1, and ABCC3 are also capable of effluxing chemotherapeutics of broad function including anti-cancer functions." (PMID 30655622, 2019). "Our current study includes assessment of select ABC superfamily gene members (including ABCB1, ABCC1, ABCC2 and ABCG1) known to act as active drug transporters to reduce accumulation of chemotherapy drugs within resistant cancer cells." (PMID 30477242, 2018). "Multidrug resistance (MDR) triggered by ATP binding cassette (ABC) transporter such as ABCB1, ABCC1, ABCG2 limited successful cancer chemotherapy." (PMID 29455646, 2018). "It has been reported that the expression of ABCC1, ABCC3 or ABCC6 was upregulated in multi-drug resistant cancer." (PMID 29228716, 2017). "Currently, the most studied ABC transporters contributing to MDR in cancer are P-gp/ABCB1 and multidrug-resistant protein 1 (MRP1/ABCC1)." (PMID 29062386, 2017). "Among these members, the three efflux transporters ABCB1 (P-glycoprotein), ABCC1 (the multidrug resistance protein 1 (MRP1)), and ABCG2 are recognized as major contributors to multidrug resistance in human cancer cells." (PMID 28880238, 2017). "Knowledge of the promoter methylation patterns of ABCB1, ABCC1 and ABCG2 in cancer cell lines will be helpful, e.g. in selecting an appropriate cell line for investigating the mode of action and/or testing the efficacy of potential chemotherapeutic drugs." (PMID 27689338, 2016). "Specifically, PacR cancer cells with transient 5-FU cross-resistance (-PacR/5-FU) showed the highest relative resistance and P-gp dependence among others with distinct MRP (ABCC1) overexpression in the PC-3 subline, as determined by Western blot analysis." (PMID 27284014, 2016). "The data on the methylation patterns of ABCB1, ABCC1 and ABCG2 provided in the present study will help in selecting appropriate cancer cell lines for investigating the mode of action and/or testing the efficacy of (epigenetic) anticancer drugs." (PMID 27689338, 2016). "The clinical relevance of the major ABC-transporters ABCB1, ABCC1, and ABCG2 for failure of chemotherapy and poor survival prognosis of cancer patients has been shown." (PMID 27092478, 2016).